IL6 (interleukin 6)
Diseases named in the same sentence as IL6 in open-access papers (continued):
Sharing a sentence is not in itself a finding about the gene and the disease.
Autoimmunity (continued). "The reduction of inflammatory markers like IL-6, TNF-α, and CRP through the incorporation of yoga into the treatment regimen of patients with autoimmune conditions, can function to further regulate the immune system and in turn provide physical and mental health benefits." (PMID 39968418, 2025). "These cells present the IL6-sIL6R complex to TH (CD4+) lymphocytes, which fix it upon the membrane gp130 and, secondary to transduction, transform into TH17 lymphocytes, secreting IL-17, with a strong pro-inflammatory role and favoring autoimmunity." (PMID 40283387, 2025). "Inhibition of IL-6/IL-21/SOCS2/STAT5 pathway and recovery of NK-cell ability to inhibit autoimmunity may be a new direction in the treatment of MG." (PMID 39346912, 2024). "Candida species could activate dendritic cells or macrophages, leading to IL-6, IL-10, TNF-α and anti-dsDNA production, thus perpetuating autoimmunity." (PMID 39637140, 2024). "Our study further validated NEAT1s role in dendritic cells which are of critical importance in autoimmunity, and we discovered that NEAT1 could function as the ceRNA to modulate IL-6 secretion via microRNA." (PMID 37343193, 2023). "The negative correlation between the proportion of ILC2s with IL-6 and IL-17A further confirmed the negative regulatory role of ILC2s in inflammation and autoimmunity." (PMID 33688303, 2021). "Moreover, deletion of IL6RA (CD126) in human Tregs elicits cytokine unresponsiveness and thus may prevent IL-6-mediated instability of Tregs, making it an attractive target to potentially boost functionality in settings of adoptive Treg therapies to contain overreaching inflammation or autoimmunity." (PMID 34408743, 2021). "In addition, aberrant TNFAIP3 signaling also leads to increased IL-6 production in dendritic cells, implicating TNFAIP3 in the development of autoimmunity in dendritic cells as well as B-cells." (PMID 33043033, 2020). "We report that TLR7, IL-6, and the adaptive immune system are essential for autoimmunity and glomerulonephritis but not for liver pathology in mice expressing the ubiquitin-binding–defective ABIN1[D485N] mutant." (PMID 31694920, 2019). "Both IL-6 and IFN-γ were required for murine mercury-induced autoimmunity." (PMID 30177931, 2018). "In summary, it is shown that a targeting of MST1 in DCs promotes IL-6 along with the expression of IL-6Rα/β and STAT3, thereby contributing to the programming Th17 cell differentiation in the inflammation that arises in both autoimmunity and fungal infection." (PMID 28145433, 2017). "Compounding these effects, IL-6 promotes hypomethylation of DNA27, 28, which could lead to a cycle of persistent inflammation in patients with autoimmunity." (PMID 28169339, 2017). "The thylcytosine dioxygenase TET2 could promote DNA demethylation to control the production of IFN-γ and IL-17 in autoimmunity, and was required to resolve inflammation by recruiting HDAC2 and repressing transcription of IL-6 through histone deacetylation." (PMID 28915632, 2017). "In autoimmunity, combination therapy with anti-IL-1β and anti-IL-6 antibody has not been tested so far." (PMID 28286780, 2017). "B cells can contribute to autoimmunity via the secretion of pro-inflammatory cytokines such as TNF-α and IL-6, but also may play a protective or regulatory role in the immune system likely depending on the particular subset and inflammatory milieu." (PMID 26047509, 2015). "In present work the cellular pathway involved in autoimmunity elicited by mercury salts encompasses endosomal TLR signaling; in turn, this signaling stimulates transcription factor NF-kB and promotes the transcription of the pro-IL-1B and IL-6 genes." (PMID 26064998, 2015). "Although the pathways have yet to be defined, taken together, these studies point to the endosomal TLRs, the proinflammatory cytokines IL-1α and IL-6 but not type I IFN as the major innate factors that drive autoimmunity following exposure to mercury." (PMID 23557436, 2013).
Autoimmunity (continued). "Since a chronic inflammatory state persists in elderly people because of the appearance of autoimmunity and chronic inflammation of the upper respiratory and urinary tracts, and so on, the levels of inflammatory markers, such as CRP, IL6, and TNFα are likely to be elevated." (PMID 22485129, 2012). "However, unbalance between cells and molecules and the increased expressions of multifunctional proteins such as IL-6, Hsp, TNF, and can unchain chronic, cumulative and irreversible processes of autoimmunities." (PMID 18716655, 2008). "Despite long-term treatment, persistent disease activity and inflammation in D2T RA may stem from a complex interplay of high baseline autoimmunity (RF/ACPA), multi-pathway immune activation (TNF-α/IL-6/JAK-STAT), comorbidities, and socioeconomic barriers limiting optimal therapy access." (PMID 40458399, 2025). "Elevated levels of IL-6, TNF-α, and IL-1β contribute to chronic inflammation and antibody production, whereas decreased production of IL-10 may explain the failure to suppress autoimmunity in ITP." (PMID 40922302, 2025). "In a murine model of type 1 diabetes, dietary treatment with ω-3 PUFAs reduced the incidence of autoimmunity in pancreatic islets, modulated the differentiation of Th- and T-regulatory cells, and decreased the levels of pro-inflammatory mediators such as IFN-γ, IL-17, IL-6, and TNF-α." (PMID 32349258, 2020). "However, in the presence of interleukin-6 (IL-6), TGF-β has also been found to promote the differentiation of naïve T lymphocytes into proinflammatory IL-17 cytokine-producing Th17 cells, which promote autoimmunity and inflammation." (PMID 30200565, 2018). "Additionally, the current findings demonstrate that the contents of IL-1, IL-6, IFN-γ and IgE in serum of mice in the OSMR-siRNA group were significantly reduced, indicating that OSMR gene silencing suppressed the autoimmunity of CAU by blocking the JAK/STAT3 signaling pathway." (PMID 30134804, 2018). "Estrogen can increase the expression of interleukin-6 in T cells and the absence of inhibitory action of progesterone may lead to overstimulated immune system and makes these patients more prone to autoimmune disorders." (PMID 25237328, 2014). "In psoriatic lesions, cytokines like IL-6, IL-12p70, IFNγ and TNFα are identified, together with chemokines like CCL2-5 and CXCL1, which shows that several of the cocktails stimulate cytokines and chemokines that to a large extent overlap with the ones expressed in different autoimmune conditions." (PMID 20663192, 2010). "Patients who experienced more negative life events had higher activation level of autoimmunity status and HAMD scores, and serum IL-6 and IL-17 levels can be decreased by SSRI treatment." (PMID 35615531, 2022). "It is worth noting that in the present study serum IL-6, IL-12, and IL-18 levels were found elevated not only in the GD but also in the TNG group, in which autoimmunity was not involved in the pathologic process." (PMID 24367378, 2013). "The complex role of IL-6 and STAT3 in both inflammation and autoimmunity could explain the lack of effect." (PMID 33897686, 2021). "In the skin of SSc patients, the infiltration and activation of plasmacytoid dendritic cells (pDCs) via PI3Kδ pathway leads to aberrant expression of TLR8 (otherwise not expressed in pDCs) that induces CXCL4, IFN-α, IL6, and TNF secretion contributing to skin fibrosis and autoimmunity." (PMID 32210969, 2020). "Mercury-induced autoimmunity, although showing clear evidence of TLR involvement does not require type I IFN, but rather shows significant dependence on proinflammatory cytokines such as IL-1α and IL-6." (PMID 23557436, 2013).
osteoporosis (332 papers, 2007 to 2026). A condition of reduced bone mass, with decreased cortical thickness and a decrease in the number and size of the trabeculae of cancellous bone (but normal chemical composition), resulting in increased fracture incidence. "First, sarcopenic obesity and osteoporosis are strongly associated with chronic low-grade inflammation, with pro-inflammatory cytokines such as IL-6, TNF-α, and IL-1 playing a critical role in developing both conditions." (PMID 40569474, 2025). "This pervasive inflammation is associated with an increased risk of osteoporosis, primarily due to the release of proinflammatory cytokines such as interleukin-1 (IL-1), interleukin-6 (IL-6), and tumor necrosis factor-alpha (TNF-α)." (PMID 39866531, 2025). "SR’s anti-inflammatory properties further contribute to its anti-osteoporotic potential as it suppresses inflammatory cytokines TNF-α and IL-6, both of which are associated with bone resorption in osteoporosis." (PMID 40496246, 2025). "Monocytes that are overexpressed exhibit elevated levels of TNF-α and IL-6, which are associated with osteoporosis." (PMID 41158629, 2025). "The results of the present study showed that the serum IL-6, IL-17 and IL-23 levels were positively correlated with the risk of osteoporosis, in agreement with previous studies." (PMID 39039571, 2024). "Increased concentrations of the inflammatory factors IL-6, IL-10, IL-12p70, IL-17, and IL-23 were associated with a greater risk of osteoporosis." (PMID 39039571, 2024). "The interleukin-6 (IL-6) gene is a proinflammatory and anti-inflammatory regulator and has a greater predisposition to fractures and osteoporosis reported." (PMID 39584868, 2024). "The crucial role of cytokines (such as TNF-ɑ, IL-6) produced in adipose tissue in increasing the risk of osteoporosis has been revealed." (PMID 38167038, 2024). "To assess the diagnostic accuracy of hs-CRP, TNF-α, and IL-6 compared to the DXA standard method for osteoporosis, we employed the ROC curve." (PMID 39263180, 2024). "In patients with RA, intracellular levels of IL-6 are typically high, and it is well-established that RA is an independent risk factor for osteoporosis." (PMID 38473934, 2024). "A recent meta-analysis reported that some polymorphisms of the IL-6 174G/C (rs1800795) and 572C/G (rs1800796) genes have been associated with an increased predisposition to fractures and osteoporosis in postmenopausal women." (PMID 39584868, 2024). "For example, isoflavones have been shown to reduce the risk of osteoporosis by decreasing the expression of main protein factors that regulate bone metabolism, such as tumor necrosis factor-α and interleukin-6, which activate osteoclasts." (PMID 37049447, 2023). "Studies have indicated that IL-6 has been implicated in a number of age-related diseases, including osteoporosis, and its levels rise with age, possibly through the P3IK/AKT, MAPK, and JAK/STAT pathways." (PMID 37475866, 2023). "For this reason, IL‐6 has shown promise as a predictor of cognitive dysfunction, which has previously been linked to bone pain and osteoporosis." (PMID 38146805, 2023). "According to the current stepwise multiple regression analysis, the independent predictors of LS and FN BMD were circulating IGFBP-3 and IL-6, which indicated that circulating cytokines were essential for preventing bone loss and osteoporosis." (PMID 37035758, 2023). "Using an in vitro model of bone loss, neutralizing IL-6 antibodies had protective effects against osteoporosis, enhancing bone mineral density, trabecular number, and thickness." (PMID 36831188, 2023). "TNF-α and IL-6 are closely related to the function of osteoclasts, and the high expression of inflammatory factors is a risk factor for osteoporosis." (PMID 36766210, 2023). "Such an association of GSs and osteoporosis arises possibly, among other things, due to increased immune inflammation and secretion of pro-inflammatory interleukins (IL-1, IL-6) and TNF." (PMID 36780036, 2023).
osteoporosis (continued). "TNFα, IL-6, and IL-1 have been linked to the formation of osteoclasts in osteoporosis patients and animal models of ovariectomy." (PMID 37239124, 2023). "It is involved in the pathophysiology of several age-related diseases such as osteoporosis and reduced IL6 signaling lowers the risk of multiple cardiovascular disorders and is associated with increased longevity." (PMID 36684006, 2022). "Our study further confirmed that IL6 is closely associated with the progression of osteoporosis in weightlessness." (PMID 35479581, 2022). "Along this line, a recent study using another IL6‐neutralizing antibody showed amelioration of osteoporosis associated with hypersecretion of IL6 due to LMNA deficiency." (PMID 33393189, 2021). "IL-6 has been suggested to be involved in the pathogenesis of osteoporosis after estrogen loss via stimulation of osteoclast differentiation." (PMID 34512388, 2021). "It has been observed that some risk factors of osteoporosis increase the production of proinflammatory cytokines, particularly IL-1β and IL-6, and can decrease OPG serum levels." (PMID 34497849, 2021). "Experimental studies revealed that IL-6 was associated with disrupted osteogenesis of bone marrow stem cells in osteoporosis models, and suppression of the IL-6 receptor prevented osteoclast-mediated bone resorption." (PMID 33807573, 2021). "In osteoporosis models, elevated pro-inflammatory cytokines, including IL-6, IL-1 and TNF-α can induce bone loss by regulating osteoclastic differentiation and activation both directly and indirectly." (PMID 34917622, 2021). "Overall, We observed the higher osteoporosis risk in IL-6 572C/G additive, dominant and recessive model." (PMID 32466786, 2020). "Circulating IL-6 levels have been associated with several inflammatory-related conditions including osteoporosis." (PMID 33007863, 2020). "Our study demonstrates that muscle atrophy induced by Lmna deficiency is sufficient to cause an osteoporosis-like deficit, which is likely due to muscle senescence–driven IL-6 expression." (PMID 32479501, 2020). "For IL-6 174G/C, the pooled odds rations indicate it was insignificantly associated with risk of developing osteoporosis in four genetic model comparisons." (PMID 32466786, 2020). "There are some studies trying to figure out the association between IL-6 gene polymorphism and osteoporosis risk, while these results acquired were conflicting." (PMID 32466786, 2020). "Several studies have been performed to investigate association between IL-6 174G/C (rs1800795) and 572C/G (rs1800796) gene polymorphisms and osteoporosis predisposition." (PMID 32466786, 2020). "First, we have only investigated the relationship between the individual gene polymorphism of IL-6 and osteoporosis." (PMID 32466786, 2020). "Since Nordstrom first reported the link between IL-6 and susceptibility to osteoporosis, many related studies had also been published, but their results were conflicting." (PMID 32466786, 2020). "So, we performed a meta-analysis designed to provide more reliable results for the association between IL-6 gene polymorphisms and osteoporosis." (PMID 32466786, 2020). "Overall, The IL-6 174G/C (rs1800795) gene polymorphism was insignificantly associated with osteoporosis vulnerability." (PMID 32466786, 2020). "The odds ratios (ORs) and 95% confidence intervals (CIs) were calculated to evaluate the association between IL-6 174G/C (rs1800795) and 572C/G (rs1800796) gene polymorphisms and osteoporosis risk." (PMID 32466786, 2020). "Osteoporosis is a common disease in the aging population and studies have shown that IL-6 is potentially implicated in its pathogenesis." (PMID 31795299, 2019). "The results of a previous study suggested an association of the IL-6 -174 G/C polymorphism with osteoporosis in postmenopausal women in a Polish population." (PMID 31301734, 2019).
osteoporosis (continued). "This indicates how a loss in estrogen can result in increased IL-6 and NFκB signaling, and a consequential increase in bone loss and osteoporosis." (PMID 30671025, 2018). "This highlights how variation in IL-6 expression within patients can alter the risk of osteoporosis in estrogen-depleted environments." (PMID 30671025, 2018). "Clinically, post-menopausal women demonstrate an increased risk of osteoporosis, and patients with certain polymorphisms in the IL-6 promoter show further increases in bone resorption rates and reduction in BMD." (PMID 30671025, 2018). "Interleukin (IL)-6 is involved in a spectrum of age-associated diseases, such as osteoporosis whose initiation and time course is affected by proinflammatory cytokines." (PMID 27128729, 2016). "Inflammatory cytokines associated with osteoporosis such as tumor necrosis factor-αand IL-6 are elevated at the onset of migraine attacks." (PMID 27610297, 2016). "In RA, IL-6 is abundantly expressed in the synovial tissue, and causes bone destruction and the development of osteoporosis by promoting synoviocyte proliferation and osteoclast differentiation." (PMID 26213566, 2015). "Several cytokines such as TNF-α, IL-1β, and IL-6 were implicated in the pathogenesis of osteoporosis." (PMID 23936022, 2013). "Studies in adult men and women, before and after menopause, have shown associations between higher levels of IL-6 and osteoporosis, and baseline IL-6 levels have predicted bone loss over a 3 year period in older adults." (PMID 22455440, 2012). "IL-6 promoted the differentiation of osteoclasts from its precursor and played an important role in the pathogenesis of osteoporosis due to estrogen deficiency." (PMID 22162676, 2012). "As an example, one of the IL6 polymorphisms tested here, rs1800796, has had both the C and G allele associated with osteoporosis depending on the race of the individual." (PMID 20565774, 2010). "Notably, GLU172, LYS66, and ARG168 have been reported as key residues targeted by MD2-TLR4-IN-1, a potential IL-6 inhibitor that mitigates inflammation-driven bone loss in osteoporosis patients." (PMID 41562931, 2026). "Furthermore, IL-6 expression was significantly increased in the femurs of mice with osteoporosis caused by tail suspension, and anti-IL-6 treatment alleviated bone loss." (PMID 40563533, 2025). "Because of its interaction with IL-6, Periostin could also potentially be used as a marker of chronic inflammation in patients with known osteoporosis, to allow a causal therapeutic approach." (PMID 39940700, 2025). "According to the sensitivity analysis, a higher energy-adjusted DII score was positively associated with osteoporosis risk (Ptrend=0.008), and elevated levels of IL-6, IL-10, IL-12p70, IL-17, and IL-23 were also associated with increased osteoporosis risk (P < 0.05)." (PMID 39039571, 2024). "Although androgens are considered the primary sex hormones in men, they block IL-6 cytokines and encourage osteoblast proliferation along with differentiation with studies showing that testosterone deficiency is associated with a risk of osteoporosis." (PMID 39200293, 2024). "For instance, it was demonstrated that patients with herpes zoster infections presented with a 4.55-fold greater risk of osteoporosis, as associated with significantly high levels of interleukin (IL)-1b, IL-6, IL-8, IL-10, and tumor necrosis factor-alpha (TNF-α)." (PMID 37113002, 2023). "Moreover, circulating IGFBP-3 and IL-6 levels were important potential diagnostic biomarkers for postmenopausal women with osteoporosis." (PMID 37035758, 2023). "IL-6 can cause osteoporosis by stimulating osteoclastogenesis to promote bone resorption." (PMID 36673366, 2023). "Pro-inflammatory cytokines such as TNF-α and IL-6 are among the high-risk factors in osteoporosis." (PMID 36673366, 2023).